INS (insulin)
Diseases named in the same sentence as INS in open-access papers (continued):
Sharing a sentence is not in itself a finding about the gene and the disease.
COVID-19 (continued). "From our perspective, an increase in insulin in COVID-19 patients could allude to a state of insulin resistance, possibly instigated by the inflammatory state induced by SARS-CoV-2 infection." (PMID 38651404, 2024). "We calculated, in the studied group of 143 hospitalized patients with the moderate/severe form of COVID-19, the state of insulin resistance at the time of inclusion, at the 4-month follow-up, and at the 12-month follow-up after the hospitalization with a post-acute episode of COVID-19." (PMID 39338165, 2024). "Clinical studies have shown that severely ill patients with COVID-19 have a high demand for insulin during peak inflammatory responses, and this significant increase in insulin demand may be due to systemic inflammation and severe IR due to critical illness." (PMID 39429741, 2024). "Moreover, COVID-19 itself can induce insulin resistance and adipose tissue infectivity, as well as cause direct damage to β-cells." (PMID 39335510, 2024). "COVID-19 patients experience a cytokine storm, with a large number of inflammatory cells affecting the function of the skeletal muscle and liver, the two main insulin-responsive organs responsible for most insulin-mediated glucose uptake." (PMID 39429741, 2024). "Furthermore, overall comorbidity burden, as well as treatment with insulin, PPI, diuretics, antiplatelets and immunosuppressants, increases the risk of severe COVID-19 in patients with eGFR <45 mL/min." (PMID 38186903, 2024). "However, in acutely ill hospitalized patients with COVID-19 and DM, insulin is recommended, based on its anti-inflammatory action and the ability to suppress ACE2 expression." (PMID 36979949, 2023). "We included only survivors of COVID-19, within 4 weeks after COVID-19 diagnosis, so we may have missed the period of critical illness when signs of deterioration of insulin function and hypermetabolism may be more pronounced and prevalent." (PMID 37460458, 2023). "Similarly, convalescent COVID-19 children also exhibited elevated levels of C-peptide, Insulin and Glucagon in comparison to control children." (PMID 37013538, 2023). "Some researchers suggest that the increase in BMI leading to severe COVID-19 may be related to increased macrophage infiltration, abnormal secretion of pro-inflammatory cytokines and insulin, leading to systemic immune dysfunction." (PMID 37752570, 2023). "However, in moderate severity COVID-19, the average blood glucose was significantly higher in the insulin-only treated group (197 ± 76 vs 168 ± 51 mg/dL; P = .001)." (PMID 36701712, 2023). "In fact, T2DM patients with COVID-19 are most recommended to be treated with insulin." (PMID 37645409, 2023). "Above, we focused on glycemic regulation that mainly reflects IR and insulin response of the liver and skeletal muscle, but adipose tissue has also been shown to be an important organ that contributes to systemic IR in patients with COVID-19." (PMID 37460458, 2023). "Similarly, insulin stimulates EPRS1 binding to SPEAR in differentiated adipocytes, consistent with increased mortality in insulin-treated COVID-19 patients." (PMID 37296097, 2023). "Like many other viral infections, COVID-19 may worsen the already dysregulated glucose metabolism, leading to an increased insulin requirement." (PMID 37510181, 2023). "Finally, MAFLD patients have a constant rise in insulin levels, which is significantly correlated with decreased respiratory capacity in COVID-19." (PMID 37185723, 2023). "In addition, in pregnant women diagnosed with GDM, insulin requirement was 8.9% in the COVID-19 (+) group and 5.1% in the COVID-19 (-) group, and the results were not statistically significant (p: 0.178)." (PMID 37927616, 2023). "Other research supports this hypothesis that insulin infusion is an effective method to achieve the expected glycemic control and could reduce the severity and mortality in diabetic patients with COVID-19." (PMID 37168726, 2023).
COVID-19 (continued). "TNF-α production is elevated in COVID-19 patients, which disrupts the insulin signaling pathway." (PMID 37187644, 2023). "On the other side, SARS-CoV2 and therapeutic agents used for COVID-19 may disrupt glycemic control, and adversely affect pancreatic beta cell functions and insulin action." (PMID 37312131, 2023). "Patients with COVID-19 often experience a decreased sensitivity to insulin due to the damage to their β-cells and may require an increase in insulin dosage, especially during feverish episodes." (PMID 37511334, 2023). "In addition, inflammatory cytokines, which are frequently elevated in the serum of patients with COVID-19, can impair insulin sensitivity and insulin secretion." (PMID 36857969, 2023). "These elevated cytokines (or cytokine storm in a severe case of COVID-19) may interfere with the insulin signalling pathway, reduce insulin production, and increase blood glucose." (PMID 37241176, 2023). "The earliest of these studies investigated erectile dysfunction drugs, contraceptives and weight-loss medications (e.g., Belviq), with more recent studies focused on insulin, oncology drugs and alleged COVID-19 treatments (e.g., dexamethasone, hydroxychloroquine or lopinavir-ritonavir)." (PMID 37174265, 2023). "In addition, diuretics were the most commonly prescribed PIM in Chinese older COVID-19 inpatients, followed by benzodiazepines and benzodiazepine receptor agonist hypnotics, insulin, antipsychotics, and rivaroxaban or dabigatran." (PMID 38001406, 2023). "Although many studies evaluated the effect of glucose and insulin level on COVID-19 outcome or severity, there are very limited studies on the effect of the glucose/insulin levels before and after COVID-19 infection like our study, which makes our findings in this regard unique." (PMID 36843827, 2023). "Similarly, convalescent COVID-19 children had elevated levels of adipsin, leptin, insulin, C-peptide, glucagon, ghrelin and Glucagon-like peptide-1 (GLP-1) in comparison to control children." (PMID 37013538, 2023). "Recent retrospective studies have suggested that insulin levels might be related to death rate in COVID-19 subjects with DM." (PMID 36619546, 2022). "Therefore, a rapid adjustment method of insulin delivery to address fluctuations in glucose levels is vital for critically ill COVID-19 patients with DKA." (PMID 35274050, 2022). "In COVID-19 patients impaired insulin secretion, insulin resistance and adipose tissue dysfunction occur together and may explain increased free fatty acids levels and triglycerides production." (PMID 36293811, 2022). "A glycemic control protocol for COVID-19 has been reported as a sliding scale for subcutaneous injection of insulin, and continuous insulin infusion adjustments were also reported in some studies of small numbers of patients undergoing continuous glucose monitoring." (PMID 35477646, 2022). "Additionally, IDE levels in monocytes, CD4+ T-cells, and CD4− T-cells were inversely correlated with circulating insulin levels in COVID-19 patients (both at diagnosis and after hospital discharge)." (PMID 36232381, 2022). "Close monitoring and tight control of blood glucose levels by oral medication or insulin treatment might be important for preventing the clinical worsening of patients with COVID-19." (PMID 35836103, 2022). "Some evidence has demonstrated that patients with severe COVID-19 and DM have a higher insulin requirement, which may be explained by the dysfunction of beta-cells or the high inflammatory process induced by the virus." (PMID 36060943, 2022). "Lastly, insulin signalling is predicted to be activated in the lungs of COVID-19 patients." (PMID 36526981, 2022). "While insulin infusion has been shown to reduce mortality in COVID-19 patients, the use of continuous glucose monitoring (CGM) should also improve glucose variability, a phenomenon linked to an increased risk of death in ICU settings, also independently of COVID-19 and diabetes." (PMID 35329890, 2022).
COVID-19 (continued). "COVID-19 may also lead to reduced physical activity and deconditioning leading to greater insulin resistance." (PMID 35853019, 2022). "Although an explanation for this observation is not the focus of the present study, a previously reported hypothesis has suggested that pancreatic beta-cells may be affected by COVID-19 reducing insulin secretion." (PMID 35160039, 2022). "Nevertheless, in this clinical context and also considering the persistence of long-term alterations on thyroid and glucose–insulin metabolism, a bidirectional relationship between COVID-19 and neuroendocrine system could be also considered." (PMID 36776681, 2022). "A plausible explanation for this is the presence and replication of the virus in the pancreatic islets and the inflammation process generated by COVID-19, which could lead to insulin resistance." (PMID 35956122, 2022). "Very interestingly, the data showed that preadmission usage of GLP-1RAs was associated with a reduction in mortality rate in patients with DM and COVID-19, independently of gender, age, gender, cardiovascular disease, hypertension, and the use of metformin and/or insulin." (PMID 36060943, 2022). "The answer to the immediate question of how to manage metabolic control in patients with severe COVID-19 is clearer: as with any critically ill patients the consensus is to use intravenous insulin with continuous glucose monitoring, preferably using a closed-loop device." (PMID 35574035, 2022). "Intensive glucose monitoring and insulin therapy to obtain optimal metabolic control may improve the outcome of COVID-19 patients." (PMID 35570587, 2022). "Metformin might be used as an alternative to insulin in patients with COVID-19; however, more studies are needed before this drug treatment can replace insulin therapy." (PMID 36079820, 2022). "Therefore, an impacted or abnormal insulin signaling pathway can directly affect COVID-19 resistance and mortality." (PMID 35711466, 2022). "Additional observation of increased omentin concentration among COVID-19 patients with intercurrent IR defined as HOMA-IR > 3 may indicate that its elevation is a compensatory mechanism improving insulin sensitivity." (PMID 34728695, 2021). "However, patients with T2DM who had COVID-19 and received insulin exhibited greater mortality (pooled OR, 2.20; P=0.002)." (PMID 34603199, 2021). "However, due to the limited number of included T1DM studies, the effects of insulin treatment on patients with COVID-19 and T1DM require further solid evidence." (PMID 34367067, 2021). "A recent review of hyperglycemic drugs’ usage concluded that early administration of insulin might have a protective effect against COVID-19 and attenuate lung injury if there is a possibility to reduce insulin resistance in patients." (PMID 34554559, 2021). "The commonly reported factors include surgery, infections including COVID-19, pericarditis, concurrent ketogenic/low carbohydrate diets, a recent change of diabetic regimen with reduction or omission of insulin dosages, nausea and vomiting, gastroparesis, pregnancy, and acute pancreatitis." (PMID 34123681, 2021). "Moreover, given the wide clinical spectrum of COVID-19 and potential to deteriorate rapidly, it is reasonable to consider early introduction of insulin on hospital admission." (PMID 34031865, 2021). "Apart from the glycosylation of ACE2 receptors that facilitates virus binding and the inflammatory process that increases insulin resistance, the hypoxia that is normally present in patients with COVID-19 is frequently accompanied by disordered cellular glucose metabolism." (PMID 33063540, 2021). "Finally, 18 articles related to the use of insulin treatment and COVID-19 were included in this meta-analysis." (PMID 34367067, 2021).
COVID-19 (continued). "Two ongoing clinical trials are assessing whether addition of DPP-4 inhibitors on the basis of insulin therapy can help improve the severity of COVID-19 (NCT04341935; NCT04542213), which may also be extended to patients without diabetes mellitus." (PMID 34867819, 2021). "Our meta-analysis mainly indicates that insulin treatment may be associated with increased mortality and severe/critical complications in T2DM and COVID-19 patients." (PMID 34367067, 2021). "They postulated that insulin infusion might be an effective measure for glycemic control in COVID-19 patients." (PMID 33687179, 2021). "High cytokine levels seen in COVID-19 could lead to beta cell dysfunction and possible apoptosis as well as an increase in insulin resistance in both liver and muscle cells." (PMID 34414048, 2021). "They showed that insulin infusion might be useful in obtaining glycemic targets and reducing mortality in diabetic patients with COVID-19." (PMID 34205044, 2021). "Four databases, namely, PubMed, Web of Science, EMBASE and the Cochrane Library, were used to identify all studies concerning insulin treatment and the adverse effects of COVID-19, including mortality, incidence of severe/critical complications, in-hospital admission and hospitalization time." (PMID 34367067, 2021). "Insulin is widely used in COVID-19 patients with hyperglycemia, especially in severe cases." (PMID 34867819, 2021). "In COVID-19 patients with DM, besides the female gender and high platelet mean volume, the use of insulin could significantly be a predictor of recovery." (PMID 33957992, 2021). "Of the total, 30.4% were on insulin treatment, 20.6% (n = 140) needed to self-isolate because of the COVID-19 infection in themselves or someone living with or experiencing COVID-19 like symptoms such as fever, persistent cough, difficulty breathing and loss of taste and smell." (PMID 34715917, 2021). "New-onset diabetes is also being reported in previously healthy individuals diagnosed with COVID-19, which may reflect coronavirus-inflicted damage to insulin-producing cells." (PMID 33565982, 2021). "There was a statistically significant difference among average duration of night sleep (P<0.001), bedtime (P<0.001), time of waking up (P<0.001), amount of insulin intake (P=0.003), daily exercise (P<0.001), and availability of the insulin (P<0.001) before and during COVID-19 crisis." (PMID 36511230, 2021). "There was a statistically significant difference among the average duration of night sleep (P<0.001), bedtime (P<0.001), time of waking up (P<0.001), amount of insulin intake (P=0.003), daily exercise (P<0.001), and presence at the gym (P<0.001) before and during the COVID-19 outbreaks." (PMID 36511230, 2021). "Metformin and sulfonylurea treatments could be associated with reduced mortality risk, while insulin treatment could be associated with enhanced mortality risk, in patients with T2DM who had COVID-19." (PMID 34603199, 2021). "We show how PHD can be used for collection and visualization of diverse datasets (wearable, clinical, omics) at a personal level, as an infrastructure for detection of presymptomatic COVID-19 cases, and biological characterization of insulin-resistance heterogeneity." (PMID 34599181, 2021). "On a molecular level, ceramides have been reported to activate inflammatory pathways in several abnormal physiological circumstances involving insulin resistance, mitochondrial dysfunction and endoplasmatic reticulum stress, which are attributed to worsen the clinical condition of COVID-19 patients." (PMID 34987511, 2021). "However, patients with COVID-19 more frequently needed insulin infusion therapy for glycemic control and showed lower osteocalcin concentrations." (PMID 34578888, 2021).
COVID-19 (continued). "In short, estrogen, especially E2, provides a protective effect on the regulation of inflammatory response and immune cell function, the influence of the cardiovascular system, insulin sensitivity and the improvement of monocyte function, thus most female patients with COVID-19 was saved from death." (PMID 34551393, 2021). "Compared with insulin alone, DPP-4is combined with insulin effectively control blood glucose levels, and their effectiveness and safety are guaranteed; additionally, good glucose control can improve the prognosis and outcome of COVID-19." (PMID 34015003, 2021). "The combination of increased ACE-2R on adipocytes along with elevated levels of insulin, leptin, and acyl moieties allows COVID-19 to create the perfect “cytokine storm” leading to severe ROS formation which destroys mitochondria, especially in patients with abundant white fat cells." (PMID 32708430, 2020). "The insulin resistance induced by COVID-19 and gluconeogenesis due to critical illness may make glycemic control challenging and potentially impact clinical outcomes." (PMID 33198177, 2020). "In our study ACE, REN, INS, KNG1, and AGT showed the highest connectivity within the complete ACE2 network and association with enriched diseases that are known to be a risk factor for a severe course of COVID-19." (PMID 33233425, 2020). "However, the impact of COVID-19 on the global economy has compromised insulin production and access." (PMID 32392473, 2020). "This renders the glycemic control in these patients an important challenge and begs the question whether the use of anti-diabetics, such as insulin and PPARγ agonists, should be used in COVID-19 patients." (PMID 32930095, 2020). "Remarkably, COVID-19 patients on metformin have better clinical outcomes than patients on insulin." (PMID 32930095, 2020). "In this review focused on biguanides, thiazolidinediones, sulfonylureas, dipeptidyl peptidase-4 (DPP4) inhibitors, glucagon-like peptide-1 receptor (GLP-1R) agonists, sodium-glucose cotransporter-2 (SGLT2) inhibitors and insulin, their profiles will be discussed in relation to COVID-19." (PMID 33195481, 2020). "Further studies are actually needed to ascertain whether plasma levels of AGEs, sRAGE, HMGB1, and S100 proteins in DM COVID-19 patients are differentially affected by conventional vs. intensive insulin therapy and are predictive of patients' outcome." (PMID 32760352, 2020). "However, the clinical relevance of this mechanism and its potential role in treatment of COVID-19 is still unclear, thus cessation of all anti-diabetic drugs except for insulin is still the current recommendation in ICU patients." (PMID 32781614, 2020). "COVID-19 may increase insulin demand and induce fever, nausea and anorexia with consequent hyperketonemia, which accentuates the gastrointestinal symptoms of infection in a vicious cycle." (PMID 32456064, 2020). "COVID-19 has worse outcomes in the obese and diabetic populations, likely because these patients are already in a proinflammatory state at baseline due to elevated levels of interleukin 6 (IL-6) from insulin and leptin resistance." (PMID 32708430, 2020). "Notably, patients on insulin may have more severe DM or require tighter glycemic control during acute illness (e.g., COVID-19)." (PMID 39835258, 2024). "While insulin is the recommended treatment for individuals hospitalized with DM, our findings suggest combining insulin with an oral antidiabetic agent may have positive effects on patient outcomes in patients with DM hospitalized for COVID-19." (PMID 39835258, 2024). "For COVID-19 hospitalization, protective factors were SGLT-2 inhibitors use (OR 0.430; 95%CI 0.257–0.719) and metformin use (OR 0.769; 95% CI 0.643–0.920), risk factors were insulin use (1.411; 95%CI 1.167–1.706) and sulfonylureas use (OR 1.226; 95% CI 1.027–1.464)." (PMID 38536830, 2024).